EGFR (epidermal growth factor receptor)
Diseases named in the same sentence as EGFR in open-access papers (continued):
Sharing a sentence is not in itself a finding about the gene and the disease.
lung cancer (continued). "In conclusion, the application of FZYA inhibited the pedigree transformation among lung cancer subtypes, thus increasing the tumor inhibitory effect and decreasing the EGFR-TKI drug resistance of tumor cells." (PMID 39735556, 2024). "Previous studies have illustrated that IGFBP2 overexpression facilitates camptothecin resistance via regulating caspase-3 in an IGF-independent manner, and it also promotes EGFR-TKI erlotinib resistance by activating IGF-1R in lung cancer cells." (PMID 38918360, 2024). "Brain metastases (BM) in patients with epidermal growth factor receptor (EGFR)‐mutant non‐small cell lung cancer (NSCLC) are very common and confer poor prognoses." (PMID 38666433, 2024). "The strongest differences are in trials of EGFR inhibitors in lung cancer and rituximab in non-Hodgkin’s lymphoma (both favoring females)." (PMID 38521835, 2024). "In EGFR-mutated and ALK-rearranged lung cancer cell lines, MCL1 translocates to the nucleus and binds to FBW7 after TKI treatment, which leads to the degradation of MCL1." (PMID 39122703, 2024). "Comparison of clinical characteristics of patients with ALK‐ and EGFR‐positive lung cancer categorized according to the CYFRA21‐1:CEA ratio." (PMID 38400801, 2024). "Most patients with lung cancer in the included studies received TT (15/16 studies reported isolated TT use), primarily epidermal growth factor receptor tyrosine kinase inhibitors (EGFR-TKI)." (PMID 38611103, 2024). "The most active compounds showed strong inhibition of EGFR and selective effects on mutant cells, suggesting their potential as therapeutic agents for lung cancer." (PMID 38625872, 2024). "Epithelial-type H358 lung cancer cells are highly sensitive to inhibition of EGFR-signalling, but resistant to ferroptosis." (PMID 39009641, 2024). "This study aimed to assess the role and effect of neoadjuvant targeted therapy (TT) versus targeted combined with chemotherapy (TC) for resectable EGFR-mutant non–small cell lung cancer (NSCLC)." (PMID 39081712, 2024). "It is also interesting that although the present case had EGFR-mutant lung cancer, symptomatic choroidal metastasis was more common in EGFR-mutant lung cancer." (PMID 38962043, 2024). "Further studies to establish a biomarker based on the biological characteristics of EGFR-mutant lung cancers are warranted." (PMID 38347279, 2024). "The objective of this study is to explore structural modifications of EGFR-TKIs in order to augment their inhibitory activity specifically against wild-type lung cancer cells." (PMID 38649732, 2024). "The OS was shorter when patients with lung cancer presented with TNM stage III–IV, EGFR wild-type mutation, and pleural fluid." (PMID 38783331, 2024). "Targeting the Wnt/β-catenin pathway in lung cancer offers a potential strategy to overcome resistance to targeted therapies like EGFR-TKIs and ALK inhibitors." (PMID 39682234, 2024). "The development of targeted therapeutics for lung cancer greatly benefits from abnormal tyrosine phosphorylation catalyzed by RPTKs, such as the Epidermal Growth Factor Receptor (EGFR)." (PMID 38182570, 2024). "For instance, commonly used predictive biomarkers for lung cancer are deletions in exon 19 of EGFR (epidermal growth factor receptor) and substitution of Leu858 with Arg (exon 21)." (PMID 39329988, 2024). "We then investigated if deleting DUSP22 would enhance the migration of HCC827 lung cancer cells by boosting EGFR activity." (PMID 38877005, 2024). "In lung cancer, it has been shown that among patients with EGFR-mutant tumors, baseline ctDNA-positive or MRD-positive status (before and/or after surgery) were associated with poor DFS in curative resected stages I to IIIA." (PMID 39123401, 2024). "The different mutation spectra in these diseases are reflected in divergent responses to EGFR inhibition: significant patient benefit in lung cancer, but limited in glioblastoma." (PMID 38548752, 2024).
lung cancer (continued). "Given that ROS1-rearranged lung cancers often feature solid growth with signet ring cells or cribriform morphology with abundant extracellular mucus, these tumors may also present with calcifications similar to those observed in EGFR-mutated and ALK-rearranged lung cancers." (PMID 39391406, 2024). "Taken together, these findings highlight the potential efficacy of β-elemene as a novel approach to overcome lncRNA H19-mediated autophagy-induced degradation of EGFR and combat resistance to gefitinib in lung cancer." (PMID 38794196, 2024). "In EGFR-lung cancer, it is difficult to predict the responder to ICI with OS prolongation based on clinical factors." (PMID 38347279, 2024). "Here, we further explored the therapeutic application of this peptide to deliver siRNAs targeting EGFR and PD-L1 to lung cancer cells." (PMID 38185193, 2024). "The study highlighted the potential of lung cancer organoid screening for Wnt targeting therapy with EGFR screening and various therapeutic strategies to combat lung cancer." (PMID 38461268, 2024). "The purpose of the study was to investigate piperlongumine as an anticancer agent and to study a combination treatment approach with EGFR-TKIs against lung cancer cells." (PMID 39449797, 2024). "In a multicenter series from our country recently published of 431 stage IV lung cancer patients, 79% were tested for EGFR, finding a prevalence of EGFR of 22%." (PMID 39421175, 2024). "Growth factor signaling pathways, such as those involving IGF-1R, EGFR, and K-Ras, exacerbate anti-apoptotic signaling in lung cancer, promoting cell survival and resistance to therapy." (PMID 39682234, 2024). "MET pathway activation is one of the most common mechanisms of resistance to osimertinib in EGFR-mutant non–small cell lung cancer (NSCLC)." (PMID 38276867, 2024). "Of note, in the two PDX models we tested only one demonstrated YAP1/WWTR1/TEAD-dependent transcription in persister cells, highlighting that other mechanisms of persistence in EGFR mutant lung cancer must exist and need to be defined." (PMID 38658677, 2024). "This study investigated the co-delivery of siRNAs targeting EGFR and PD-L1 to human lung cancer cells." (PMID 38185193, 2024). "Later studies demonstrated that FOXM1 overexpression leads to resistance to gefitinib, an EGFR small molecule inhibitor used as first-line therapy to treat NSCLC in lung cancer cell lines and primary human lung cancer cells." (PMID 39594778, 2024). "Approximately 88% of newly diagnosed lung cancer cases in Canada are non-small cell lung cancers (NSCLC), of which approximately 15% harbor a mutation in the epidermal growth factor receptor (EGFR) gene." (PMID 39195310, 2024). "This highlights the potential of MA as an EGFR-TKI sensitizer, particularly in lung cancer cells with KRAS mutations and resistance to Osimertinib." (PMID 38515565, 2024). "For example, gastric, colon, and lung cancers were reported to induce anoikis resistance and metastasis through epidermal growth factor receptor (EGFR) signaling." (PMID 39333870, 2024). "Meanwhile, CAFs were proved to promote the activation of signaling pathways such as the PI3K-AKT-mTOR pathway, which can lead to resistance to EGFR TKIs in lung cancer 19,20." (PMID 39034310, 2024). "Epidermal growth factor receptor (EGFR)-activating mutations are prevalent in non-small cell lung carcinoma (NSCLC), which is the predominant type of lung cancer." (PMID 38474400, 2024). "As the first successful targeted therapy against lung cancer, EGFR-targeted therapy has contributed to improving the quality of life and survival of patients with lung cancer." (PMID 38451729, 2024). "This implies that constitutively-active EGFR mutants can promote lung cancer cell migration, partly through the enhanced EGFR activity resulting from DUSP22 deletion." (PMID 38877005, 2024). "In summary, our study has provided insights into the tumor-intrinsic mechanisms of DUSP22 in suppressing lung cancer via EGFR." (PMID 38877005, 2024).
lung cancer (continued). "We performed immunocytochemistry (ICC), which helps to reveal the distribution of EGFR on the surface of lung cancer cells using anti-EGFR primary antibodies." (PMID 39453005, 2024). "Through analysis of an independent lung cancer single-cell dataset, we showed that co-expression of EGFR and MUC1 was specific to tumor cells in the tumor microenvironment." (PMID 39664199, 2024). "Further, we show that combinatorial targeting of the Hippo pathway and EGFR is highly effective in EGFR mutant lung cancer cells and patient-derived organoids, suggesting a new therapeutic strategy for EGFR mutant lung cancer patients." (PMID 38658677, 2024). "In EGFR-mutant lung cancers, re-treatment with an EGFR-TKI is regarded as a treatment option, although the RR (5–25%) is much lower than the RR in treatment-naïve tumors (70–80%)." (PMID 38398169, 2024). "The epidermal growth factor receptor, EGFR, is frequently activated in lung cancer and glioblastoma by genomic alterations including missense mutations." (PMID 38548752, 2024). "Of 205 EGFR‐positive lung cancer patients, 172 cases of advanced or recurrent EGFR‐positive lung cancer were analyzed, excluding recurrence‐free cases and comutations with ALK." (PMID 38400801, 2024). "Epidermal growth factor receptor‐targeted (EGFR‐targeted) therapies show promise for non‐small cell lung cancer (NSCLC), but they are ineffective in a third of patients who lack EGFR mutations." (PMID 38463398, 2024). "Preemptive combination to treat EGFR-mutant lung cancer: osimertinib, afatinib, and capmatinib (OAC)." (PMID 38188499, 2024). "Last decade, targeted therapies, such as epidermal growth factor receptor tyrosine kinase inhibitors (EGFR-TKIs) have made giant progress in lung cancer." (PMID 37436674, 2024). "In conclusion, the interplay between EGFR mutation and SMARCA4 deficiency in NSCLC underscores the complexity of lung cancer biology." (PMID 39465834, 2024). "The development of targeted therapies, such as EGFR tyrosine kinase inhibitors (EGFR TKIs), has greatly advanced lung cancer treatment." (PMID 39318388, 2024). "Evidence is limited on preferences of Japanese patients and physicians in treatment for epidermal growth factor receptor (EGFR)‐mutant non‐small cell lung cancer (NSCLC)." (PMID 38196301, 2024). "USP14 controls epidermal growth factor receptor (EGFR) fate in lung cancer by deubiquitinating the endocytic adaptor Eps15." (PMID 39164728, 2024). "A panel of 10 EGFR mutant lung cancer patient-derived xenografts (PDX) was used to characterize Hippo signalling in the setting of osimertinib treatment." (PMID 38658677, 2024). "Concerning mutant EGFR and mutant BRAFs, two studies have been inspired so far by the emergence of BRAFV600E in treatment-refractory EGFRL858R lung cancers as they become resistant to EGFR-targeted therapies." (PMID 38485987, 2024). "LPCAT1 had never been reported in cervical cancer but was reported to promote gefitinib resistance through upregulation of the EGFR/PI3K/Akt signaling pathway in lung carcinoma, and it has been recognized as a promising prognostic biomarker in liver cancer." (PMID 38656879, 2024). "A retrospective study on advanced EGFR mutant lung carcinoma in Pakistani patients reported similar demographics to our study, with a majority of male patients (54.5%) and advanced stage IV NSCLC (90.9%)." (PMID 39429333, 2024). "Non–small cell lung cancer (NSCLC) accounts for approximately 85% of lung cancer cases, and mutant EGFR is one of its most common oncogenic drivers (10%–40%), which is associated with poor prognosis and limited therapeutic efficacy." (PMID 38546390, 2024). "For example, EGFR exon 19 and 21 alterations or MET exon 14 skipping mutations occur almost exclusively in lung carcinomas, while BCR-ABL rearrangements are characteristic mainly of hematological malignancies." (PMID 38612902, 2024).
lung cancer (continued). "We report that LAMC2 is an important EGFR TKI sensitive gene with oncogenic functions in lung cancer cells and mice xenograft." (PMID 37542131, 2023). "Afatinib (GiotritTM, BIBW-2992) is the first covalent EGFR inhibitor approved by the FDA for lung cancer, and is a second-generation EGFR TKI, which was marketed in July 2013." (PMID 37669923, 2023). "Src activation is important in the acquisition and maintenance of resistance to EGFR inhibitors in lung cancer, in addition to the well-established involvement of Src kinases in tumor growth." (PMID 36902280, 2023). "This study aims to develop and validate an 18F-FDG PET/CT radiogenomic model on the basis of 18F-FDG PET/CT radiomics and clinical-parameter EGFR to predict the PFS stratification of SBRT in lung-cancer patients." (PMID 37109413, 2023). "To understand the effects of a high-fat diet (HFD) on lung cancer progression and biomarkers, we here used an inducible mutant epidermal growth factor receptor (EGFR)-driven lung cancer transgenic mouse model fed a regular diet (RD) or HFD." (PMID 37929799, 2023). "Admittedly, the current study is not without limitations for confirming the role of MET fusions in the development of lung cancer resistance to EGFR/ALK-TKIs, and further exploration of these rare actionable genomic alterations is needed." (PMID 36829199, 2023). "EGFR, a transmembrane receptor tyrosine kinase, is overexpressed in many solid tumors, such as lung cancer, breast cancer, and glioblastoma." (PMID 36874921, 2023). "Among lung cancers, non-small cell lung cancer (NSCLC) accounts for 85% of all cases, and epidermal growth factor receptor (EGFR) gene mutations have been found in at least 59.4% of Asian NSCLC patients." (PMID 38035047, 2023). "To corroborate the relevance of T cell activation in the therapeutic efficacy of EGFR-TKIs, we re-analyzed a clinical cohort of 8 patients with EGFR mutant lung cancers." (PMID 36817465, 2023). "The study also involves the creation of a hybrid system for the treatment and diagnosis of lung cancer, which utilizes PEGylated gold nanoparticles to target EGFR." (PMID 37242668, 2023). "They conclude that in mutant lung cancer cells overexpressing EGFR and resistant to tyrosine kinase inhibitors, Sortilin acts as a tumor suppressor, whereas in other cancers it promotes malignant cell behavior." (PMID 37576898, 2023). "This randomized clinical trial compares the use of gefitinib plus chemotherapy with gefitinib monotherapy in patients with untreated EGFR-mutant non–small cell lung cancer brain metastases." (PMID 36753281, 2023). "BaP additionally promotes the expression of growth factors and their receptors, such as the epidermal growth factor (EGF) and EGF receptor (EGFR), the major contributors to lung cancer development." (PMID 37631277, 2023). "Mitogen-inducible gene 6 (Mig6) fails to mediate the degradation of mutant EGFR, and deletion of Mig6 promotes tumor initiation and mutant EGFR-driven lung cancer progression." (PMID 37813845, 2023). "The cold atmospheric plasma (CAP) technique combined with iron oxide-based magnetic nanoparticles downregulated epidermal growth factor receptor (EGFR) and inhibited lung cancer cells by depressing pERK and pAKT." (PMID 37538179, 2023). "Previous studies have reported functional interactions between EM 3 and HER-2 in urothelial and breast cancer, and further interplay between EMP 1 and EGFR in lung cancer." (PMID 37629198, 2023). "Currently, survival benefit of immunotherapy in advanced non‐small cell lung cancer (NSCLC) with EGFR exon 20 insertions (ex20ins) is controversial, though it generally indicates poor response and activity." (PMID 35608132, 2023). "Acquired resistance represents a bottleneck to epidermal growth factor receptor (EGFR) tyrosine kinase inhibitor (TKI) treatment in lung cancer." (PMID 37387596, 2023).
lung cancer (continued). "The ADAURA trial is currently examining the effects of EGFR inhibitors after surgery for localized lung cancer, including early-stage lung cancer, and has reported positive outcomes." (PMID 36765844, 2023). "For instance, the epidermal growth factor receptor (EGFR) plays an essential role in lung cancer and depends on its expression status among the population." (PMID 36820064, 2023). "Tyrosine kinase inhibitors (TKIs) of the epidermal growth factor receptor (EGFR) have shown survival improvements in the treatment of patients with EGFR-mutant lung cancer as first line therapy." (PMID 36647832, 2023). "One of these interplays is MET–EGFR crosstalk, which was reported to be involved in therapeutic resistance to EGFR inhibitors in colon and lung cancers." (PMID 37679999, 2023). "We did not observe statistically relevant associations between GR expression and other common lung cancer driver mutations, including KRAS and EGFR." (PMID 37035141, 2023). "To verify the significant role of BIM in mediating the sensitivity to gefitinib, we transfected EGFR-mutant lung cancer cells (HCC827) with siRNA targeting BIM or PD-L1." (PMID 36894581, 2023). "Nevertheless, our study highlights the potential of a rational combination strategy to improve the therapeutic efficacy of osimertinib in EGFR mutant-driven lung cancers." (PMID 36817465, 2023). "This technique facilitated a specific uptake of RBCEVs with EGFR-positive lung cancer cells in vivo, supporting the versatile applications of extracellular vesicles in cancer therapies." (PMID 38067344, 2023). "While MIG6 and AXL are both correlated with EMT and EGFR signaling pathways, how AXL, MIG6 and EGFR interplay in lung cancer remains elusive." (PMID 37834326, 2023). "The BC‐mediated alternative splicing (AS) of IMPAD1 resulted in the induction of the epithelial–mesenchymal transition and resistance to EGFR‐TKI in lung cancer." (PMID 36650118, 2023). "Nevertheless, a second-site mutation of EGFR Thr790Met, MET gene amplification, etc. confers lung cancer acquire resistance to these EGFR TKIs." (PMID 37004022, 2023). "Small-molecule inhibitors against EGFR, such as erlotinib and gefitinib, have also been shown to be significantly effective against EGFR-mutant lung cancer." (PMID 37947595, 2023). "In a xenograft mouse model of EGFR-mutant lung cancer, LLC cells transferred EGFR with the deletion mutation E746-A750 to the surface of the DCs via exosomes." (PMID 37915578, 2023). "Most lung cancer cells that are resistant to epidermal growth factor receptor (EGFR) inhibitor erlotinib exhibit a mesenchymal phenotype." (PMID 38188677, 2023). "Despite the fact that EGFR-TKIs have yielded several significant benefits for lung cancer patients, the emergence of resistance to EGFR-TKIs has been a substantial impediment to improving treatment outcomes." (PMID 36902280, 2023). "Accumulating studies show that dysregulation of EGFR spatial distribution and stability also critically contributes to abnormal EGFR signaling and lung cancer progression." (PMID 37813845, 2023). "Lung cancer patients harboring EGFR activation benefit from the targeted therapies of gefitinib, a specific EGFR inhibitor." (PMID 37181807, 2023). "In this study, we utilized a variety of cell models that harbored common driver mutations in lung cancer including KRAS substitution (A549) and EGFR activation mutations (HCC827, H1975)." (PMID 36709476, 2023).